BRAF (B-Raf proto-oncogene, serine/threonine kinase)
Diseases named in the same sentence as BRAF in open-access papers (continued):
Sharing a sentence is not in itself a finding about the gene and the disease.
melanoma (continued). "BRAF inhibitors and MEK inhibitors were a breakthrough in the treatment of melanoma and around 15–20% of tumors finally show primary resistance to this treatment, and moreover, some patients even develop acquired resistance to therapy." (PMID 35837089, 2022). "Another clinical trial, IMspire150 evaluated atezolizumab (anti-PDL-1) with cobimetinib and vemurafenib (BRAF/MEK inhibitors) (triple therapy) on advanced, locally resectable melanoma patients." (PMID 35308763, 2022). "Under the treatment with BRAF inhibitors or MEK inhibitors, tumor cells including melanoma finally adapt to drug treatment by upregulation of autophagy, suggesting the availability of autophagy inhibitors in combination with targeted therapies." (PMID 36034839, 2022). "For each of the main systemic treatment modalities for melanoma (anti-PD-1 therapy, combined PD-1 and CTLA-4 blockade, and targeted BRAF and MEK inhibition), response rates have been shown to correlate with OS; PFS also has been shown to correlate with OS." (PMID 35449104, 2022). "We show that genetic inactivation of PPP6C increases MITF and target gene expression, decreases sensitivity to BRAF inhibition, and increases phosphorylated MITF in a BRAF(V600E) mutant melanoma cell line." (PMID 35368039, 2022). "In BRAF-mut melanoma cells, SEMA6A coordinates actin cytoskeleton remodeling by the RhoA-dependent activation of YAP and dual BRAF/MEK inhibition by dabrafenib+trametinib induces SEMA6A/RhoA/YAP axis." (PMID 35440004, 2022). "Accordingly, glembatumumab vedotin, a gpNMB-targeted MMAE-conjugated ADC, resulted in a 39% ORR in a phase I/II study conducted among patients with advanced melanoma refractory to ICI and BRAF/MEK inhibition, with acceptable toxicity (NCT00412828)." (PMID 35159045, 2022). "Consistent with a key role of RAS in the orchestration of drug resistance in melanoma, NF1 was the top hit in a large-scale short hairpin RNA (shRNA) screen for genes that, when lost, confer resistance to BRAF inhibition in melanoma cell lines." (PMID 35234863, 2022). "The use of immunotherapy and targeted BRAF and MEK inhibitors therapy to treat advanced melanoma has improved clinical outcomes for many patients." (PMID 36058945, 2022). "It is important to note that the genetic classification of melanomas has become particularly important in determining whether a patient is eligible for immuno- or targeted therapy, as the administration of either immuno- or targeted therapy depends on the BRAF status." (PMID 36119516, 2022). "Currently, anti-PD-1 and anti-CTLA4 antibodies and BRAF/MEK inhibitors are the mainstay of treatment of advanced, inoperable or disseminated malignant melanoma." (PMID 35406444, 2022). "Genetic changes in BRAF and RAS result in hyperactivation of the RAS/RAF/MEK/ERK (MAPK) signalling pathway in most melanomas." (PMID 36613640, 2022). "Furthermore, adjuvant treatment with immune checkpoint blockade (or BRAF pathway targeted therapy in BRAF mutant melanoma patients) improved relapse-free survival (RFS) compared to placebo in phase 3 clinical trials and is now regarded as standard of care in high-risk stage III melanoma patients." (PMID 35810563, 2022). "Resistance to BRAF/MEK inhibition and comparatively low response rates to immune checkpoint inhibitors remain clinical challenges in the treatment of melanoma." (PMID 35366166, 2022). "In the context of melanoma, pre-clinical investigations have demonstrated that the plasma membrane calcium ATPase PMCA4 inhibits the migration and metastatic activity of BRAF-mutant melanoma cells." (PMID 36232957, 2022). "Although BRAF and mitogen-activated protein kinase (MEK) inhibitors has improved current situation of melanoma therapy, challenges still remain regarding how to overcome drug resistance and meet the demand of more effective targeted therapies." (PMID 35055084, 2022).
melanoma (continued). "Among all genes analyzed, DUSP4 appeared to have a major role in controlling the viability of BRAF- and NRAS-mutant melanoma cells." (PMID 35580987, 2022). "As regards melanoma, activation of the PI3K–Akt pathway promotes resistance mechanisms to both BRAF and MEK inhibitors." (PMID 35335966, 2022). "Rapidly accelerated fibrosarcoma B-type (BRAF) and mitogen-activated extracellular signal-regulated kinase (MEK) inhibitors have revolutionized melanoma treatment." (PMID 35492830, 2022). "Ultraviolet radiation induces a range of gene alterations, including those in BRAF, RAS, C-Kit and NF1, and promotes the activation of inflammation in melanoma, according to accumulating evidence." (PMID 36498797, 2022). "Notably, more than half of the patients who tested BRAF V600E positive only through ddPCR presented later with sentinel lymph node metastases, suggesting that ddPCR is the most suitable methodology for detecting the low-frequency BRAF V600E-positive melanoma clones in patients’ tissues." (PMID 35887633, 2022). "In BRAF (V600E)-mutant melanoma, the sex-determining region Y-box 10 (SOX10) is suppressed, and BRAF signaling-activated TFEB S142 phosphorylation is promoted." (PMID 35461253, 2022). "Dabrafenib (GSK2118436) is a BRAF kinase inhibitor, whose antiproliferative effect has been shown in vitro in V600EBRAF melanoma and in human colon tumor xenografts." (PMID 35628540, 2022). "In melanoma cells, the expression of receptor tyrosine kinases such as EGFR, PDGFRB, and ERBB3 increases upon exposition to BRAF/MEK inhibitors." (PMID 35565444, 2022). "Three combinations of inhibitors of mutant BRAF and MEK have been approved by the FDA for treatment of advanced unresectable melanoma." (PMID 36212431, 2022). "They explored the relative frequency of genetic factors(BRAF/NRAS/p16CDKN2A) known to play an important role in melanoma development, and their distribution among different melanoma tissues and disease progression sites by sequencing DNA from tissue samples." (PMID 36091077, 2022). "The relative expression level of the hub genes was reverified in melanoma cell lines, and showed that HIF1A, IL1B, HMOX1, MMP3, CDKN2A and TIMP1 were upregulated, while PTEN, PRKCA, ATF3 and BRAF were downregulated in melanoma samples." (PMID 36226170, 2022). "The decreasing effect on the oncogenic BRAF protein level was particularly evident with ITF2357, which resulted the most efficacious HDAC inhibitor in SK-MEL-28 and A375 melanoma cells." (PMID 36009541, 2022). "Collectively, these data suggest that combined immune checkpoint blockade and HDAC inhibition can stimulate T cell immunity against human UM in vitro and BRAF, NRAS, and NF1 wildtype melanoma in vivo." (PMID 34753889, 2022). "As yet, there is no completed randomised, prospective data to inform the optimum sequence of BRAF/MEK inhibitors and CPI therapies in patients with BRAF-mutant melanoma." (PMID 35366166, 2022). "Activating BRAF alterations at the V600E locus is a well-known driver in pan-cancer and FDA-approved therapeutic targets for colorectal cancer, melanoma, non-small cell lung cancer, and anaplastic thyroid cancer." (PMID 36072793, 2022). "Identifying constitutive BRAF-MEK-ERK signaling as the key oncogenic driver in HCL has implemented inhibitors of BRAF and MEK licensed for melanoma treatment in several clinical trials." (PMID 35205704, 2022). "Additionally, the loss of NF1 can result in RAS resistance to negative feedback, and NF1 inactivation in melanoma harboring BRAF mutation results in a selective advantage by reversing oncogene-mediated suppression of RAS, which is driven by ERK-induced negative feedback." (PMID 36181568, 2022). "CDK4/6 inhibitors have the potential to augment immune-mediated therapeutic responses to existing standard-of-care treatments for melanoma, including both ICI and BRAF/MEK-targeted therapies." (PMID 35444175, 2022).
melanoma (continued). "Our study demonstrates that in BRAF- and NRAS-mutant MITF-proficient melanoma, the DUSP4 MAPK phosphatase restricts MAPK activation and prevents oncogenic overdose through modulation of MITF function." (PMID 35580987, 2022). "In patient‐derived short‐term melanoma cultures, higher DDR1 and DDR2 protein levels were detected in BRAF mutant MM099 and MM029 and NRAS mutant MM165 cells with the MITFlow, SOX10low, and AXLhigh de‐differentiated phenotype signature." (PMID 34957688, 2022). "Several BRAF kinase inhibitors, such as Vemurafenib, Dabrafenib, and Encorafenib, which target BRAFV600E or BRAFV600K, have been used to treat advanced malignant melanoma." (PMID 36499102, 2022). "The goal of this meta-analysis was to provide a useful tool to guide the clinician towards the best therapeutic option among the different combinations of BRAF and MEK inhibitors used in melanoma treatment." (PMID 36612138, 2022). "Differential abundance analysis in control SKMEL28-EV cells revealed significant depletion of BRAF and MAPK1 (also known as ERK2) targeting sgRNAs, in line with the known addiction of BRAFV600E mutant melanomas to the MAPK pathway." (PMID 35798875, 2022). "Using the BRAF inhibitor dabrafenib, the MEK inhibitor trametinib and the chemotherapeutic agent cisplatin, we first derived a panel of melanoma cell lines that respectively developed resistance to these three therapeutics." (PMID 34535764, 2022). "BRAF inhibitors, such as vemurafenib, are the most effective FDA-approved treatments for BRAF positive melanoma." (PMID 35164181, 2022). "Genetic alterations in the BRAF, NRAS, or NF1 genes define melanoma subtypes and lead to the MAPK pathway hyperactivation." (PMID 35156321, 2022). "In 2016, two main treatment strategies for melanoma patients, ICI and BRAF/MEKi, were registered in Europe." (PMID 36497248, 2022). "Vemurafenib was the first selective oral BRAF small molecule inhibitor, approved in 2011 by the FDA, for advanced melanoma treatment and in 2013 a second selective BRAF inhibitor, Dabrafenib, was approved by the FDA." (PMID 36119516, 2022). "The work considered 70 unresectable stage III–IV melanoma patients undergoing baseline 18F-FDG PET/CT; these were assigned to the BRAFV600 (35 patients, 100 lesions) or BRAF wild-type group (35 patients, 79 lesions) according to the mutational status." (PMID 35453977, 2022). "Therefore, the genetic duet of BRAF V600E and TERT promoter mutations represents an effective therapeutic target in cancer, so that combined targeted therapy may improve the overall survival of melanoma patients with TERT promoter mutations." (PMID 35903534, 2022). "For example, in melanoma, the high expression of Axl makes tumor cells resistant to MAPK pathway inhibitors, and the combination of Axl antibody conjugate and BRAF/MEK inhibitor can synergistically inhibit the growth of tumor cells." (PMID 35310910, 2022). "The input for the app includes two drop-down menus of treatments and radio buttons to choose the (sub-) group of patients corresponding to the major melanoma genotypes (All, NRAS, BRAF, Triple WT)." (PMID 36139469, 2022). "Melanoma cells can also uptake lipids from an aged TME through the induction of the FA transporter FATP2, generating specific age-related tolerance to BRAF/MEK inhibitors." (PMID 35912100, 2022). "In melanoma, PDK1 was revealed to facilitate resistance of targeted BRAF inhibition through mediating oncogene-induced senescence induced by BRAFV600E." (PMID 35961973, 2022).
melanoma (continued). "Our results indicate higher protein expression of SEMA6A in BRAF-mut compared with BRAF-wt melanoma patients and show that SEMA6A is a prognostic indicator in BRAF-mut melanoma from TCGA and DFCI patients cohorts." (PMID 35440004, 2022). "Among patients with BRAF-mutant melanoma and brain metastases (MBM), treatment with the BRAF inhibitors dabrafenib or vemurafenib leads to response rates of 20% and 38%, respectively, in patients with radiotherapy-naïve disease." (PMID 35258806, 2022). "In summary, for exploiting the full potential of combined BRAF/MEK inhibition, all possible BRAFi/MEKi combinations were evaluated in three melanoma cell lines." (PMID 36230853, 2022). "Nine therapeutic drugs (including BRAF and MAPK/ERK kinase (MEK) inhibitors and cytotoxic T lymphocyte antigen 4 (CTLA4)‐ and PD1-directed mAbs) have been approved by the FDA for melanoma in the past three decades." (PMID 36209184, 2022). "We engineered the BLISH, which included metastatic melanoma spheroids with a perfusable BV and LV pair, to evaluate the effect of administration of the BRAF and PI3K inhibitors on melanoma intravasation." (PMID 36026581, 2022). "BRAF/MEKi also promote the recruitment and/or expansion of cytotoxic CD8 + T-cells, increase T-cell killing and enhance T-cell recognition of melanoma cells by promoting HLA class I and antigen expression on tumour cells." (PMID 35366166, 2022). "Small molecule inhibitors of kinases such as MEK, BRAF, EGFR, ALK, and KRAS promoted GSDME cleavage by CASP3 and resulted in lung cancer and melanoma regression." (PMID 35964070, 2022). "After assessing the MEK and BRAF inhibitor resistance phenotypes of A375 melanoma model cell lines in both 2D and 3D tissue culture, we next evaluated each line for sensitivity to combination MEK/BRAF inhibitor treatment." (PMID 36358868, 2022). "Inhibition of IGF2BP1 can enhance the role of BRAF inhibitors and BRAF-MEK inhibitors in BRAFV600E melanoma." (PMID 35935853, 2022). "Elevated BRAF-BRAF and BRAF-CRAF dimers were consistently observed in MEFs and primary melanocytes expressing NRAS mutants with strong melanoma-driving potential." (PMID 35672316, 2022). "Altogether, these data suggest the existence of a feedback loop upon metabolic stress in NRASQ61mutant melanomas between the RAS pathway and the glycolytic route, connecting BRAF, PFKFB2, PFK1, SOS1/2 and NRAS." (PMID 36402789, 2022). "Following the results obtained through the combination of BRAF and MEK inhibitors in BRAF-mutant melanoma, the same combination was prospectively assessed in BRAF-mutant NSCLC." (PMID 36230797, 2022). "The response of PDCs and five established melanoma cell lines (two NRAS-positive, one wild type, and two BRAF V600-positive) was evaluated toward a panel of 527 oncology drugs using high-throughput drug sensitivity and resistance testing." (PMID 34837846, 2022). "The development of targeted therapies (BRAF/MEK inhibitors) and immunotherapy have had a major impact on the treatment of melanoma." (PMID 35624662, 2022). "One study on BRAF and MET inhibitors in melanoma patients even showed an inferior result under the intermittent therapy compared to continuous therapy." (PMID 35273301, 2022). "MEK1 P124L mutation was observed in a metastatic tumor biopsy from a drug resistant melanoma patient upon MEKi AZD6244 treatment, while dual inhibition of MEK and BRAF can overcome the acquired resistance." (PMID 35966590, 2022). "FATP1 (SLC27A1) accelerates melanoma initiation, and FATP2 (SLC27A2) confers melanoma resistance to BRAF and MEK inhibition by promoting FA uptake from the microenvironment." (PMID 35764645, 2022). "The use of targeted kinase inhibitors, including BRAF and MEK inhibitors, combined with immune checkpoint inhibitors, has significantly improved the progression-free and overall survival of melanoma patients." (PMID 35216449, 2022).
melanoma (continued). "While the association between ICI and microbiome has been well described, it remains to be assessed for MAPK-directed therapy (BRAF/MEK inhibitors—BRAF/MEKi), which is nowadays one of the key elements in melanoma treatment." (PMID 36233289, 2022). "Second and to our opinion most relevant, we show that SEMA6A is involved in the mechanisms that regulate the sensitivity of BRAF-mut melanoma cells to dual BRAF/MEK inhibition therapy and acts as a crucial mediator of melanoma-stroma communication." (PMID 35440004, 2022). "Targets of these small molecule KIs include BRAF, which occurs in about 50% of melanoma patients, and MEK, a downstream signaling target of BRAF in the MAPK pathway." (PMID 35560144, 2022). "In microenvironment-mimicking co-culture condition, fibroblasts confer to melanoma cells a proliferative stimulus and protect them from targeted therapies, whereas SEMA6A depletion rescues the efficacy of dual BRAF/MEK inhibition." (PMID 35440004, 2022). "Patients with melanoma brain metastases respond to immune checkpoint inhibitors (ICI) and BRAF/MEK inhibitors (BRAF/MEKi); however, they are underrepresented in clinical trials." (PMID 36497248, 2022). "Only Dabrafenib has been reported to have potent inhibitory effect against BRAF-mutant melanoma and NRAS-mutant melanoma cell lines." (PMID 35436996, 2022). "Aside from genetic regulation by BRAF, the overactivated MAPK pathway in melanoma also contributes to increased glycolysis." (PMID 36003368, 2022). "In melanoma, AKT1 and AKT2 activation are more commonly found in BRAF-mutant tumors, while AKT3 hyperactivity is more common in BRAF wild-type melanomas." (PMID 35158840, 2022). "ERK-mediated MAPK signal pathway reactivation often occurs after inhibiting BRAF and MEK in melanoma treatment." (PMID 36551302, 2022). "As no therapeutic agents have been approved specifically for NRAS-mutant melanoma, our aim was to compare the benefit of PLA1A in the BRAF- and NRAS-driven melanoma cancer population." (PMID 33723350, 2021). "In current treatment protocols, combined BRAF and MEK inhibition is a standard of care for treating BRAFV600E-mutant melanoma." (PMID 34621046, 2021). "Pimasertib alone is better than dacarbazine for improving progression-free survival in patient with BRAF- and NRAS-mutant melanoma." (PMID 34607583, 2021). "Another therapy recently approved by the FDA is the combination of atezolizumab with BRAF inhibitor vemurafenib and MEK inhibitor cobimetinib, resulted in safe tolerability and prolonged progression-free cell survival in melanoma patients." (PMID 33807778, 2021). "One clinical study compared prognostic significance between a cohort of BRAF-mutant and NRAS-mutant melanoma patients, revealing a lower relative survival in patients with NRAS-mutant melanoma." (PMID 33807778, 2021). "Cutaneous side effects include cutaneous squamous cell carcinoma, which develops in the context of compensatory signaling through wildtype BRAF and MEK in non-melanoma skin cells." (PMID 34277419, 2021). "The remodelled matrix was found to promote BRAF‐independent ERK activation through FAK signalling, thereby enabling drug tolerance and melanoma cell survival." (PMID 34459009, 2021). "Additional research is needed to define other cellular targets and effective treatment strategies in both newly diagnosed and kinase BRAF and MEK inhibitor-resistant melanoma patients." (PMID 33613844, 2021). "The MAPK-ERK pathway, which includes BRAF, NRAS, MEK1/2, and ERK1/2, is instrumental to the evolution of melanoma." (PMID 34071176, 2021). "NRAS and BRAF both play a part in the MAPK pathway, which are thought to contribute to melanoma development." (PMID 34350118, 2021). "Accordingly it has been reported that ERK1 and ERK2 overexpression results in cell death in BRAF and NRAS‐mutant melanoma cells." (PMID 32767816, 2021).